IL10 (interleukin 10)
Diseases named in the same sentence as IL10 in open-access papers (continued):
Sharing a sentence is not in itself a finding about the gene and the disease.
cancer (continued). "Our pan-cancer analysis reveals its consistent upregulation in 33 malignancies, including GBM, where it strongly correlates with immunosuppressive molecules (PD-L1, CTLA-4, TGF-β, IL-10), suggesting a potential universal role in immune evasion." (PMID 41438981, 2025). "Moreover, considering the reported immunosuppressive effect of DEX released from IL-10-stimulated DCs, it is essential to investigate the immunostimulatory and immunosuppressive effects of DEX in cancer vaccine therapy in future studies." (PMID 40458410, 2025). "One of the limitations of this study is that there was no further combined blockade of IL-10 or IL-17 to assess the efficacy of combined blockades in the treatment of malignant tumors." (PMID 40040705, 2025). "Cytokines like IL-10 and IL-6 are key to regulating immune responses within the pre-metastatic niche (PMN), and they contribute to forming the immunosuppressive environment typical of cancer progression." (PMID 41583453, 2025). "In contrast, the M2-like phenotype is characterized by immunosuppressive and pro-tumorigenic properties due to the secretion of IL-10, transforming growth factor (TGF)-β, and proteolytic enzymes like MMP-9 that contribute to ECM remodeling and facilitate cancer invasion and metastasis." (PMID 40002754, 2025). "IL-10–Fc fusion proteins increase oxidative phosphorylation in exhausted CD8+ TILs, and CAR-T cells coexpressing IL-10 can eradicate solid tumors across multiple cancer types while also generating stem-like memory T cells." (PMID 40481182, 2025). "One possible explanation is that TIC10‐induced TRAIL activates the noncanonical NFκB2 pathway in cancer cells, leading to the production of cytokines such as IL‐6, IL‐10, and GM‐CSF." (PMID 40673385, 2025). "Current studies on the efficacy of IL-10 fusion proteins mainly focus on cancer, but their ability to mediate CD8+ T-cell proliferation, activation, and metabolic reprogramming also gives IL-10 fusion proteins significant potential in the anti-inflammatory field." (PMID 41312367, 2025). "Conclusively, Pereskia bleo leaves could potentially modulate the anti-cancer immune response by up-regulating IFN-γ, IL-12, IL-18, perforin, and granzyme B, while downregulating IL-8 and IL-10 in healthy blood samples." (PMID 39619199, 2024). "However, factors released by cancer cells that suppress the immune response, such as TGF-β, VEGF and IL-10, inhibit the maturation of DCs." (PMID 39188717, 2024). "GB exhibits an immune-privileged nature characterized by limited lymphocytic infiltration, cytotoxic T cell exhaustion, recruitment of pro-tumorigenic TAMs, downregulation of cancer cells’ MHC I complexes, and abundance of immune-inhibitory molecules such as IL-10 and TGFβ." (PMID 38473776, 2024). "To date, there have been no ICKs incorporating IL-10 that have advanced to clinical trials for cancer treatment." (PMID 39204319, 2024). "Despite this, it has recently been observed that IL-10 may play a role in CD8+ T cell activation and proliferation in cancer and chronic inflammation." (PMID 39199571, 2024). "Human-derived cytokines interleukin-2 (IL-2), IL-4, IL-6, IL-12, IL-10, tumor necrosis factor α (TNF-α), and interferon-γ (IFN-γ) could be detected in all cancer cell–bearing mice by cytokine level measurement." (PMID 39606226, 2024). "The expansion of IL-10+, TIM-1+, PD-1+ and GrB+ Bregs has been correlated with progressive disease stage and poorer prognosis in patients, highlighting the intricate functional roles of these cells in cancer pathogenesis, prognosis and outcomes." (PMID 39346706, 2024). "Hypoxia and increased synthesis of vascular endothelial growth factor (VEGF), macrophage colony-stimulating factor (M-CSF), IL-6, IDO, extracellular adenosine, and immunosuppressive cytokines, including IL-10 and TGF-β, characterize the cancer site's immunosuppressive milieu." (PMID 38962577, 2024).
cancer (continued). "There were greater numbers of PD-L1- and IL-10-expressing macrophages (CD68+ cells) and PD-L1- and IL-10-expressing dendritic cells (CD11c+ cells), as well as PD-L1- and IL-10-expressing macrophages in the PBMC and cancer mucosa, in AGC patients than in EGC patients." (PMID 38197259, 2024). "IL-10 does not affect cancer cell extravasation, but rather influences later stages of the metastatic cascade." (PMID 39681594, 2024). "Cancer controls (B) receiving only AOM showed statistically the highest number of pro-inflammatory cytokines (TNF-α and IL-6) and lowest anti-inflammatory cytokines (IL-10) in their tissue homogenates." (PMID 38191592, 2024). "Previous studies pointed to an up-regulatory effect of M2 TAMs and TAFs on the expression of IL-10 and TGF-β, IL-6 and MMPs, and the endothelial mesenchymal transition (EMT)-related genes, e.g., vimentin in cancer cells which subsequently dampened the efficacy of ICD." (PMID 37612575, 2024). "Numerous studies have appraised IL-10 concentrations in diverse specimens obtained from cancer patients, consistently reporting elevated IL-10 levels in MA compared to non-malignant ascites." (PMID 38279997, 2024). "Cancer cells also directly inhibit the immune system through molecules like vascular endothelial growth factor (VEGF), prostaglandin E2, transforming growth factor-β (TGF- β), and interleukin-10 (IL-10), which suppress cytotoxic T-cell function." (PMID 38893120, 2024). "Here, we have found the prominent expression of il-6, il-10 and il-1β receptors on respective cancer cells, without any noticeable change in the expression of vegf receptor." (PMID 38304256, 2023). "IL10 is primarily produced and expressed by M2/TAM, lymphocytes and cancer cells." (PMID 36835413, 2023). "Pegilodecakin (PEGylated IL-10; PEG-IL-10; AM0010) is an IL-10-based antineoplastic agent that stimulates systemic immune responses and enhances intratumoral CD8+ T lymphocyte invigoration in cancer patients, according to early preclinical studies." (PMID 37483629, 2023). "There is also emerging evidence that IL-10 can be ‘non-classical’ and pro-inflammatory in the context of cancer." (PMID 37568698, 2023). "Furthermore, we previously found that certain cytokines and transcriptional factors, including IL-6, IL10, IL-27, STAT, and NF-kB, regulate PD-L1 expression in various cancers." (PMID 36757936, 2023). "Daily consumption of dark tea can achieve cancer prevention by inhibiting pro-inflammatory cytokines TNF-α, IL-1β, and IL-6 and increasing anti-inflammatory cytokines IL-10 and IL-22, which is mainly attributed to the down-regulation of the NF-κB signaling pathway." (PMID 37764687, 2023). "For example, IL-10, IL-13, and TGF-β from cancer cells and macrophages induce angiogenesis." (PMID 35895109, 2023). "Next, to identify the responsible factors activating NF-κB, we have treated cells (EP and LP) with MDSC supernatant in presence/absence of IL-6, IL-10 and IL-1β neutralizing antibodies, keeping untreated cancer cells as a control." (PMID 38304256, 2023). "IL-10 might have direct effects on T cells because pegylated IL-10 induced systemic activation and polyclonal expansion of CD8+ T cells in cancer patients." (PMID 36581713, 2023). "The role of monocytes producing IL-10 and TGF-beta in cancer is ambiguous." (PMID 36768201, 2023). "Tregs may secrete regulatory cytokines such as IL-10 and TGF-β, which help to maintain the immunosuppressive microenvironment and facilitate cancer cells in evading immune surveillance." (PMID 37632832, 2023). "Furthermore, feladilimab enhanced the production of IFNγ, IL17, IL10, and TNFα by TCR-activated healthy donor and cancer patient PBMC." (PMID 37593752, 2023). "Other immunoproteome biomarkers (IL-6, IL-10, MIP-1α) identified to be associated with genital inflammatory scores likely relate to cancer-induced inflammation rather than a host defense response to dysbiotic vaginal microbiota." (PMID 35196323, 2022).
cancer (continued). "Our findings suggest that salivary IL-6, IL-10, and TNF levels may be used as biomarkers for OM occurrence and grade in patients with cancer." (PMID 35476641, 2022). "As a result, cancer cells become “invisible” to the cells of the immune system through down-regulation of HLA class I antigens or TAAs, and through the production of immune suppressive cytokines such as TGF-beta, IL-4, and IL-10." (PMID 35892820, 2022). "Interestingly, TAMs (CCL2, CD86, and IL10), M1 [INOS(NOS2), IRF5, and COX2(PTGS2)] were significantly correlated with SHC1 expression in the three cancers." (PMID 35601500, 2022). "Macrophages that infiltrate the TME secrete cytokines, such as IL-6, IL-10, TNF-α, and TGF-β, which may enhance cancer cell stemness and EMT." (PMID 35565306, 2022). "RT-qPCR showed the expression of CHI3L1, IL-10, RETNLB (Fizz1), and Arg1, to confirm the M2 macrophages The results showed that the expression level of both CD68 and CD206 were significantly increased in cancer tissues compared with paracancerous tissues." (PMID 35637970, 2022). "Macrophages affect the cancer population indirectly by producing cytokines like IL6, IL10, and IL2." (PMID 35294447, 2022). "IL-1β, IL-12, and IL-10 were all upregulated in the supernatants from the macrophage-with-cancer-cell groups compared with those from the control, cancer-cell, DLL3-overexpressed-cancer-cell, and macrophage groups." (PMID 35382168, 2022). "Besides, there were significant correlations between the concomitant expression profiles of INPP5A/HLA-G1, INPP5A/IL-10, and INPP5A/MMP-21 in the patients with invaded cancer cells into the adventitia." (PMID 36437782, 2022). "On the contrary, cancer cells induce the dysfunction of effector T cells through upregulation of inhibitory molecules (e.g., PD-L1 and CTLA-4) or synthesis of immunosuppressive cytokines (e.g., TGF-β, IL-1, IL-6, and IL-10)." (PMID 36726985, 2022). "To this end, we compared the relationships between OM grade, oral mucosal dryness, and inflammatory mediators (Interleukin (IL)-1β, IL-6, IL-10, IL-12p70, tumor necrosis factor (TNF), prostaglandin E2, and vascular endothelial growth factor) in patients with cancer and in healthy volunteers (HV)." (PMID 35476641, 2022). "Leptin, interferon‐γ, IL‐1β, IL‐10, adiponectin, and ghrelin did not demonstrate any significant difference between groups when individuals with cancer cachexia were compared against non‐cachectic patients or healthy participants." (PMID 35080147, 2022). "In particular, IL-10 inhibits cytotoxic T-cell activation by downregulating major histocompatibility complex (MHC) expression on cancer cells and antigen-presenting cells (APCs), and prevents antigen specific T cells from recognizing cancer cells." (PMID 36497050, 2022). "It is interesting to note that miR-193a provides a possible link between cancer stemness and immunoevasion, as PBX1 (which is another predicted target of miR-193a), as well as the transcriptional activator for the immunosuppressive cytokine IL-10." (PMID 35216394, 2022). "This decrease in MNCs proliferation may be associated with the presence of Th2-type immunosuppressive cytokines, such as IL-4, IL-10 and TGF-β, which are mainly responsible for immunosuppression in different types of cancer." (PMID 36661506, 2022). "According to the content of IL-1β, IL-6, IL-8, IL-18, and IL-10, the subgroup of luminal B (HER2-positive) cancer differed from the rest of the luminal subtypes, which suggested that it was HER2 status that was the determining factor influencing on the content of cytokines in saliva." (PMID 36286034, 2022). "Among their multitude of functions, IL-10 is well-known to inhibit T cell activation, whereas TGF-β inhibits T cell activation and proliferation and promotes epithelial to mesenchymal transition, favoring cancer cell migration and invasion." (PMID 35159208, 2022).
cancer (continued). "Whereas these cytokines may lead to co-occurring immune stimulation and immunosuppression in cancer patients, concentrations of cytokines MIF, TNFα, interleukin 6, interleukin 8, interleukin 10, interleukin 18, and TGFβ are increased." (PMID 36579330, 2022). "In the ScRNAseq merged datasets analyzed in other cancers and chronic inflammatory diseases, IL10 was not among the DEG." (PMID 35418195, 2022). "Considering the inter-triggering mechanism of cancer progression and inflammation, we assessed the production of pro-inflammatory cytokines, including IL-6, TNF-α, and IFN-γ, and the anti-inflammatory cytokine IL-10 in CAC mice in colon tissue and serum." (PMID 33996624, 2021). "Defects in MHC I proteins, infiltration of suppressive cells such as MDSCs, and secretion of immunosuppressive cytokines and chemokines such as IL-10, TGF-β, and indoleamine 2,3-dioxygenase (IDO) are the main mechanisms of cancer immune evasion that reduce the effectiveness of cancer vaccines." (PMID 34332576, 2021). "The first five core paths of COVID-PF are IL-10 signaling; constitutive signaling by aberrant PI3K in cancer; PI3K/AKT signaling in cancer; PI5P, PP2A, and IER3 regulate the PI3K/AKT signaling; and transcriptional regulation by the AP-2 (TFAP2) family of transcription factors." (PMID 33768100, 2021). "Moreover, the expression of IL2, IL10, IL12, LAYN in pre-exhausted T cells were consistent with the expression of genes in other cancer, suggesting that pre-exhausted T cell have common features in immune microenvironment." (PMID 34434188, 2021). "Although IL-15 is not as effective as IL-10, we demonstrated the potential of IL-15 in cancer immunotherapy." (PMID 33912464, 2021). "The results revealed a significant increase in IL-10 secretion in the cancer serum-derived exosome-treated group but no significant change in TGF-β secretion." (PMID 34717645, 2021). "In nonmetastatic cancer patients, T cells were negatively correlated with IL-6 and IL-10 and were positively correlated with IL-4 and TNF-α." (PMID 34712741, 2021). "In CML, AML, and ALL, cancer cells express TGF-β and IL-10 to reduce immunogenicity." (PMID 34867958, 2021). "High preoperative serum levels of IL-10 correlated with poor prognosis in CRC patients and patients with cancer recurrence after surgery had a significantly higher level of IL-10, indicating that IL-10 could be considered as the prognostic biomarker in CRC." (PMID 35008550, 2021). "IL-10 secreted by MDSC can inhibit IRF8 expression by upregulating pSTAT3-Dnmt1/3b in colon epithelial cells, which promotes the transformation of normal epithelial cells into cancer cells." (PMID 34689842, 2021). "In addition to TGFB1 and IL10, gene expression of IFNG, IL6, and CXCL8 were all significantly increased (p < 0.05) in mesenchymal samples for more than half of the cancer types." (PMID 35096592, 2021). "In the context of the cancer-immunity cycle, soluble signals such as cytokines represent signal 3 to balance TCR signaling either to a potent immune response (IL-2, IL-17) or a tolerogenic state (IL-10, IL-6)." (PMID 33466674, 2021). "It was found that, under the situation of irradiation, the concentration of TNF-α in the medium had a much higher level but IL-10 became much lower than those of nonirradiated cancer cells." (PMID 33867819, 2021). "This could be followed by anti-IL10 treatment, combined with targeting of the CLL microenvironment, particularly NLC, to decrease the survival of remaining cancer cells." (PMID 35008174, 2021). "We propose that muscle-derived IL10, CXCL1 and CCL4 are, at least in part, responsible for the exercise-mediated upregulation of CASP3 and 7 gene expression and consequently their increased protein levels in PC and other cancer cells." (PMID 34359731, 2021). "Our previous study also showed that patients with active cancer had higher plasma IL-10 levels and mortality rates than those without cancer." (PMID 34070883, 2021).
cancer (continued). "The higher the Log IL10, the better the FACT-PCA in the non-cancer and pre-C/T subgroups." (PMID 34073990, 2021). "When cancer occurs, IL-10 and TGF-β secreted by TAMs can prevent an antitumor immune response by inhibiting the function of antigen-presenting cells and effector T cells, leading to the escape of cancer cells and the formation of an immunosuppressive TME." (PMID 34683963, 2021). "Despite all of these observations, the effects of IL-10 in cancer therapy remain inconclusive due to the lack of data from large-scale clinical trials, and the scant evidence gathered from human in vitro testing systems." (PMID 34769278, 2021). "Interestingly, the CMV-derived IL-10 also promotes the proliferation and migration of cancer cells, linking chronic infections such as CMV to cancer formation." (PMID 34307156, 2021). "A 4-NQO carcinogen-driven mouse model of oral cancer revealed that the initial inflammatory profile present in pre-cancer (dominated by IFN-gamma and IL-17 along with other inflammatory mediators) was succeeded by anti-inflammatory cytokine IL-10 as the lesions progressed to SCC." (PMID 35048056, 2021). "Using in vitro co-cultures of activated PMEL CD8+ T cells and B16F10 cancer cells, and ex vivo production of PD1+TIM-3+CD8+ T cells, respirometry analysis revealed an increase in oxygen consumption rates (OCR) upon treatment with IL-10-Fc." (PMID 34621543, 2021). "Although in some diseases therapy and research, MSCs modified by IL10 gene have been applied 16, in-depth study using BMSCs modified by IL10 have not been carried out about cancer." (PMID 32742480, 2020). "That calcium EP can upregulate IL-10 secretion from both CD4+ and CD8+ T cell cocultures in a dose dependent manner indicates that high dose calcium administration may inhibit anti-cancer immune responses as directed by exposed BMDMs47." (PMID 33244152, 2020). "Moreover, IL-10 was reported to play important role in cancer development and to strongly induce the phosphorylation of STAT3 in cancer cells." (PMID 33372604, 2020). "Interestingly, M2b macrophages, induced by IgG immunoglobulin complexes and LPS, upregulate IL-10 and chemokine (C-C motif) ligand 1 (CCL1) expression and have been reported in the context of both, allergy as well as cancer." (PMID 32708690, 2020). "The population of these cells in cancer outnumbers the cells with a CD4+CD25+Foxp3+ phenotype, they have the ability to release immunosuppressants such as IL10 and TGF-β1, and the number of these cells increases progressively in HCC along with the stage of the disease." (PMID 32488850, 2020). "We compared the expression of the 15 immune gene cancer tissues and adjacent tissues in the TCGA-BLCA cohort and found that the expression of the CCR9, IL7, PTGER4, IL10, CTSG, and ZBTB16 proteins in the adjacent tissues was significantly higher than that in the cancerous tissues (P < 0.05)." (PMID 32655621, 2020). "One of the mechanisms of the suppressor action of MSCs on the adaptive immune response in inflammation and cancer is believed to be their inhibition of maturation of antigen-presenting dendritic cells under the action of various soluble factors - TGF-β, IL-10, NO, and PD-1." (PMID 32024236, 2020). "Hence, glufosinate prevents the protumoral effects of IL10‐stimulated macrophages by improving CD8+ T‐cell proliferation and migration, and by inhibiting capillary formation and cancer cell invasion." (PMID 32885605, 2020). "In previous studies of gastric cancer, IL-6 has been shown to induce the M2 differentiation and increase the expression of TGF-β and IL-10 in TAMs via promoting STAT3 phosphorylation and activation, and this phenomenon augments the proliferation and migration of cancer cells." (PMID 33114183, 2020). "The IL-6 released from these macrophages, but not IL-10 and GM-CSF, suggests that cancer cells are promoting their proliferation in a paracrine manner." (PMID 32655574, 2020).